SIGLEC1 (sialic acid binding Ig like lectin 1)
Diseases named in the same sentence as SIGLEC1 in open-access papers (continued):
Sharing a sentence is not in itself a finding about the gene and the disease.
systemic sclerosis (9 papers, 2010 to 2024). A chronic disorder, possibly autoimmune, marked by excessive production of collagen which results in hardening and thickening of body tissues. "Recently it was reported that Siglec-1 (CD169) expression on monocytes can be used as a biomarker for IFN-I responses in systemic sclerosis and SLE." (PMID 20478071, 2010). "In blood, expression of surface SIGLEC-1 is restricted to CD14+ monocytes, and has been previously reported to be increased in several other autoimmune diseases, including rheumatoid arthritis, systemic sclerosis (SSc) and primary biliary cirrhosis." (PMID 30053827, 2018).
glioblastoma (7 papers, 2015 to 2025). The most malignant astrocytic tumor (WHO grade IV). "SIGLEC1+ myeloid infiltrates were present in patients with glioblastoma (n = 2), herpes simplex encephalitis (n = 2) and cerebral infarction (n = 2), as well as toxoplasmosis (n = 1), cerebral abscess (n = 2) and post-transplant lymphoproliferative disorders (n = 1, PTLD)." (PMID 33986412, 2021).
endometrial cancer (6 papers, 2021 to 2025). Primary or metastatic malignant neoplasm involving the endometrium (mucous membrane that lines the endometrial cavity). "On the other hand, SIGLEC1 expression was correlated with immune cell infiltration in endometrial cancer and survival." (PMID 34394090, 2021).
lung carcinoma (6 papers, 2018 to 2025). "Similarly, in lung cancer or osteosarcoma lung metastases, RTM-TAMs are characterized by high levels of MARCO, scavenger receptor (SIGLEC1 (CD169)), and fatty acid-binding protein 4 (FABP4) expression, which is also characteristic of alveolar macrophages." (PMID 39941714, 2025).
multiple sclerosis (5 papers, 2007 to 2022). A progressive autoimmune disorder affecting the central nervous system resulting in demyelination. "We aimed to evaluate SIGLEC1 (CD169) as a biomarker in multiple sclerosis (MS) and Neuromyelitis optica spectrum disorder (NMOSD) and to evaluate the presence of SIGLEC1+ myeloid cells in demyelinating diseases." (PMID 33986412, 2021). "Here, we report that, after accounting for interferon treatment, patients with multiple sclerosis (MS) and neuromyelitis optica spectrum disorder (NMOSD) did not have increased expression of SIGLEC1 on monocytes in the peripheral blood." (PMID 33986412, 2021).
breast tumors (4 papers, 2020 to 2025). "RNA sequencing of breast tumors further confirmed that SIGLEC1 (CD169) expression was associated with mature tertiary lymphoid structure (TLS), and Treg and Breg signatures." (PMID 36831605, 2023). "A possible relationship between type I IFNs and CD169-expression on Mo-M was supported by mRNA data from primary human breast tumors, where mRNA expression for the gene SIGLEC1 encoding CD169 significantly correlated with IFNA4 (P=6.25e-04) and IFNB1 (P=5.53e-41)." (PMID 37404831, 2023). "More recently, breast tumor cells induced CCL8 expression in infiltrating TAMs, which in turn induced Siglec1 and enhanced monocyte recruitment and tumor cell motility." (PMID 33072601, 2020).
Sjögren’s Syndrome (4 papers, 2021 to 2022). "Sialic acid binding Ig like lectin 1 (Siglec-1), a biomarker of the activation of type I IFN pathway, was highly expressed in monocytes of SjS patients and was positively correlated with the EULAR Sjögren’s Syndrome Disease Activity Index (ESSDAI) score." (PMID 35309355, 2022). "Finally, we examined this IRG signature (ISG15, SIGLEC1, STAT1 RSAD2, IFI27 and IFI44L) in peripheral blood mononuclear cells (PBMCs) collected from a smaller cohort of healthy controls, disease controls, AAV and primary Sjogren’s syndrome (pSS) patients." (PMID 33859290, 2021).
invasive breast carcinoma (3 papers, 2016 to 2022). A carcinoma that infiltrates the breast parenchyma. "Furthermore, higher numbers of CD163 and SIGLEC1 single- and double-positive TAMs were reported in invasive breast cancer." (PMID 36358879, 2022). "Having established that SIGLEC1 is significantly expressed only by Br-TAM, we performed immunofluorescent staining using anti-SIGLEC1 and anti-CD163 antibodies on tissue biopsies from patients with invasive breast cancer and benign lesions." (PMID 30930117, 2019).
allergic reaction (2 papers, 2022 to 2024). "Among the most significant genes, SIGLEC1 interacts with T cells, and EMR4P is related to an allergic reaction." (PMID 35493728, 2022).
colon cancer (2 papers, 2021 to 2025). "Additionally, the association between SIGLEC1 mRNA expression and the clinical characteristics of colon cancer patients in the TCGA cohort was examined." (PMID 39744582, 2025). "Herein, we first investigated SIGLEC1 differential expression in both colon tumors and normal tissues, and the results showed significantly downregulated SIGLEC1 expression in the tumor tissues than that in the normal tissues." (PMID 39744582, 2025). "Simultaneously, patients with colon cancer with lower SIGLEC1 expression exhibited lower survival rates." (PMID 39744582, 2025).
Nematode infection (2 papers, 2019 to 2025). "Also unique to this GO term was the upregulated gene sialic acid binding Ig like lectin 1(SIGLEC1) which is activated in monocytic cells to interact with the gene mucin 1 (MUC1); a gene shown to respond during GI nematode infections." (PMID 40906414, 2025).
ovarian tumors (2 papers, 2023). "The increased expression of SIGLEC1 is closely related to tumor formation and metastasis, and the increased expression of ICOS leads to poor prognosis and significantly increased PDCD1 expression in ovarian tumors." (PMID 37895197, 2023).
primary biliary cholangitis (2 papers, 2022 to 2025). Primary biliary cholangitis (PBC) is a chronic and slowly progressive cholestatic liver disease of autoimmune etiology characterized by injury of the intrahepatic bile ducts that may eventually lead to liver failure. "In addition, SIGLEC-1 has been shown to be elevated in RA, autoimmune thyroiditis, and primary biliary cholangitis (PBC)." (PMID 36297311, 2022).
psoriasis (2 papers, 2016 to 2024). An autoimmune condition characterized by red, well-delineated plaques with silvery scales that are usually on the extensor surfaces and scalp. "Of the five genes (BATF2, HRNR, SIGLEC1, SLC4A11, CXCL10) uniquely identified by multiDE (with Bonferroni adjustment), four were found to be closely related to psoriasis." (PMID 27334001, 2016).
rheumatic disease (2 papers, 2022). "Levels of SIGLEC-1 expression on monocytes of 203 SSc patients were determined in a cross-sectional and longitudinal analysis using multicolor flow cytometry, then compared to 119 patients with other rheumatic diseases and 13 healthy controls." (PMID 36297311, 2022).
amyotrophic lateral sclerosis (1 paper, 2021). Amyotrophic lateral sclerosis (ALS) is a neurodegenerative disease characterized by progressive muscular paralysis reflecting degeneration of motor neurons in the primary motor cortex, corticospinal tracts, brainstem and spinal cord. "No increase in SIGLEC1+ cells was noted in the brain of a patient who died of amyotrophic lateral sclerosis (ALS)." (PMID 33986412, 2021).
Arthritis (1 paper, 2016). Inflammation of a joint. "The 70 up regulated and 30 down regulated genes were analyzed using PGMapper and Siglec1 was found to relevant to arthritis." (PMID 27480124, 2016).
burn (1 paper, 2019). A traumatic injury involving interruption of tissue cohesiveness that results from exposure to caustic chemicals, extreme heat, extreme cold or excessive radiation. "Burn injury significantly diminishes the expression of Siglec1 in BM EBIMØs suggesting a role for the myeloid derived MØ in the maturation of pro erythroblasts into poly/orthochromatic erythroblasts and reticulocytes." (PMID 31824951, 2019).
cardiac amyloidosis (1 paper, 2025). Cardiac amyloidosis is a condition whereby cardiac tissue is infiltrated by amyloid fibrils. "PON3, SIGLEC1, and IL-6 demonstrated a statistically non-significant trend of a weak-to-moderate association with MACE in cardiac amyloidosis." (PMID 41007815, 2025).
colon adenocarcinoma (1 paper, 2025). "For example, in colon adenocarcinoma, SIGLEC1, as an immune-related gene, has been confirmed to be significantly associated with immune cell infiltration in the tumor microenvironment and patient prognosis." (PMID 40406544, 2025).
diarrhoea (1 paper, 2022). "Some of the DEGs in diarrhoea-susceptible sheep, enriched in GO terms and sub-network analysis, included IL-6, LOC101121216 (serum amyloid A), SIGLEC1, CHI3L1, S100A9, CD14, CD68, CD86, Ovar-DRB1, IL1RL1, LOC101103238 (CXCL5), CCL22 and IL1RN." (PMID 35576023, 2022).
mixed connective tissue disease (1 paper, 2021). Mixed connective tissue disease (MCTD) is a rare autoimmune disorder that is characterized by features commonly seen in three different connective tissue disorders: systemic lupus erythematosus, scleroderma, and polymyositis. "In the NMOSD patients, one of the four patients with increased SIGLEC1 expression had the additional diagnosis of a mixed connective tissue disease (MCTD), a disease that is also associated with increased type 1 interferon activity." (PMID 33986412, 2021).
Neisseria meningitidis infection (1 paper, 2022). "Macrophages can rely on Siglec1-mediated phagocytosis for Neisseria meningitidis infection." (PMID 36389805, 2022).
neuronal ceroid lipofuscinosis (1 paper, 2020). "Notably, Siglec1 inactivation in mouse models of neuronal ceroid lipofuscinosis significantly reduced neuron loss and the retinal thinning associated with the condition." (PMID 31837604, 2020).
pulmonary TB (1 paper, 2021). "Although different SIGLEC1 polymorphisms have been previously associated with pulmonary TB in a small sized cohort, the functional consequences of those particular variants on Siglec‐1 activity remain to be elucidated." (PMID 33489013, 2021).
secondary-progressive MS (1 paper, 2021). "In contrast, in five samples from patients with secondary-progressive MS (SPMS) with histologically classified chronic lesions, we found CD68+HLA-DR+ infiltrates of varying density, but almost no SIGLEC1 expression." (PMID 33986412, 2021).
Stroke (1 paper, 2025). Sudden impairment of blood flow to a part of the brain due to occlusion or rupture of an artery to the brain. "Ten proteins (including BCAN, NCAN, beta-NGF, SIGLEC1 and VWC2) were common to both the acute and convalescent stroke phase, but there were also differing examples." (PMID 40316737, 2025).
testicular cancer (1 paper, 2024). A primary or metastatic malignant neoplasm that affects the testis. "Furthermore, The Human Protein Atlas database suggests that in RC and testicular cancers expressing Siglec1 gene, the outcome is unfavourable." (PMID 38268823, 2024).
tumor (161 papers, 2012 to 2026). "Firstly, the outcomes from the univariate Cox regression analysis indicated that SIGLEC1 expression, tumor stage, T/N/M stage, and age were linked to the survival rate of patients with CRC." (PMID 39744582, 2025). "Several studies have suggested that SIGLEC1, which encodes CD169, can act as a tumor-associated macrophage biomarker." (PMID 35127943, 2022). "A recent study demonstrated a cross talk between tumor cells and tumor-associated macrophages (TAMs) via SIGLEC1, CCL8, and CSF1, suggesting that the gene signature of TAMs correlated with poor clinical outcomes." (PMID 35223504, 2022). "SIGLEC1 is a sialic binding receptor mainly expressed by macrophages; the infiltration of SIGLEC1+ macrophages in CRC was associated with tumor progression." (PMID 36506313, 2022). "For example, macrophages that express Siglec-1 (CD169) have been shown to present tumor antigens to cytotoxic T cells, and Siglec-1 deficient macrophages result in inhibition of anti-tumor immunity." (PMID 33247183, 2020). "Consistent with this, in Cox multivariate analysis after adjusting for clinical parameters such as ER, PR, Her2, grade, and tumor size, SIGLEC1 high expression was independently significantly associated with shorter DSS (HR = 1.42, p = 1.85 × 10−0.4)." (PMID 30930117, 2019). "However, little is known about Siglec1 on monocytes, but minor data demonstrated that higher expression of Siglec1 on tumor-associated macrophages correlated to worse prognosis in cancer patients." (PMID 39315092, 2024). "SIGLEC1 (CD169) is a novel biomarker of tumor-associated macrophages." (PMID 32074080, 2020). "Overall, these outcomes indicated that SIGLEC1 played a crucial part in the CRC tumor immune microenvironment." (PMID 39744582, 2025). "Through in vitro cell experiments and in vivo animal models, we will verify the effects of YHJD upregulating SIGLEC1 expression on immune cell function and how this effect promotes anti-tumor immune responses." (PMID 39744582, 2025). "Further studies should examine the expressions of CD47 and CD24 at the transcriptional levels to further understand the mechanism of CD47/SIRPα and CD24/Siglec‐1 pathways in the anti‐tumor immune response." (PMID 41354057, 2025). "In investigating the correlation between SIGLEC1 and tumors, despite meticulous efforts to select representative and rigorously screened samples, tumor heterogeneity remains a complex and largely uncontrollable factor." (PMID 39744582, 2025). "SIGLEC1 exhibited differential expression between the tumor and control samples, and improved survival was observed in patients with increased SIGLEC1 expression." (PMID 39744582, 2025). "By demonstrating that SMLR1 is upregulated in CRLM and interacts with tumor-associated macrophages (TAMs) via MRC1 (CD206) and SIGLEC1 (CD169), this research unveils a novel mechanism of immune evasion and tumor progression." (PMID 39324019, 2024). "TAMs play a pivotal role in tumor progression by serving as the primary source of CCL8, whose interaction with SIGLEC1 orchestrates a positive feedback regulatory loop between tumor cells and TAMs, amplifying tumor cell motility." (PMID 39410029, 2024). "recently confirmed that microglial genes (CX3CR1, TMEM119, and P2RY12) were mainly expressed in the periphery, while activated macrophage genes (TNF, CCL2, LYZ, CCR2, CXCR4, and SIGLEC1) were predominantly detected within the core tumor regions." (PMID 37731483, 2023). "CD169+ macrophages (Siglec-1) can phagocytose dead cancer cells during the initial phases of tumor progression." (PMID 37143666, 2023). "Some studies inhibit tumor growth through intravenous injections of abiotic sialic acid on the surface of melanoma tumor cells to guide the recognition and binding of SIGLEC1 by macrophages." (PMID 37207210, 2023). "Unexpectedly, the expression of SIGLEC1 was positively correlated with tumor grade, and patients with high levels of SIGLEC1 had lower overall survival." (PMID 36266311, 2022).
tumor (continued). "We demonstrated that TAMs are the major source of CCL8, and CCL8 and SIGLEC1 engage in a tumor cell-TAM regulatory loop, involving TNF-α, which in turn enhances their expression and leads to increased tumor cell motility." (PMID 30930117, 2019). "This intratumoral heterogeneity can lead to varying SIGLEC1 expression levels across different regions or cells, potentially influencing the composition and function of the tumor microenvironment, thereby complicating and obscuring the relationship between SIGLEC1 and its microenvironment." (PMID 39744582, 2025). "Our study demonstrated that SIGLEC1 not only serves as an independent prognostic factor but also displays a strong correlation with immunological parameters and immune cell infiltration within the tumor microenvironment." (PMID 39744582, 2025). "Additionally, monocytes and particularly tumor-associated macrophages (TAMs) (LAM2 APOE + macrophages and SIGLEC1 + macrophages) were prominently closer to EMT hotspots as compared to EPI hotspots." (PMID 39529126, 2024). "SIGLEC1-positive macrophages are closely related to T cell-mediated anti-tumor immunity." (PMID 37207210, 2023). "In tumor tissues with a high SIGLEC1/CD68 ratio, there was an increase in the infiltration and function of cytotoxic lymphocytes, based on the expression of the T cell receptor CD3 complex subunit (CD3E), natural cytotoxicity receptor (NCR1), and interferon gamma (IFNG)." (PMID 36266311, 2022). "Similarly, RNA sequencing data from human GBM tissues confirmed that microglial genes were expressed in the periphery and that activated macrophage genes and SIGLEC1 were expressed within the central tumor regions." (PMID 36266311, 2022). "FGL2, FUCA1, PLEKHO1, and SIGLEC1 were highly expressed in DC and might influence its number in tumor." (PMID 35127943, 2022). "The expression of SIRPA, LILRB1, LILRB2, Siglec1, Siglec7, Siglec9, PDCD1, CD163 and MARCO are preferentially expressed on Mono01, Mono02 and Macro03, suggesting their tumor-promoting roles." (PMID 40755770, 2025). "pRMS tumor cells affect the macrophages through SIGLEC1 and CSF1R receptors, possibly preventing tumor cell phagocytosis." (PMID 41373578, 2025). "TAMs are a major source of CCL8, which, together with SIGLEC1, participates in a tumour cell–TAM positive feedback regulatory loop that leads to increased tumour cell motility." (PMID 40434054, 2025). "In tumor cells of CRC, SIGLEC1 can further prevent the progression of tumors by promoting the activity of immune cells." (PMID 39744582, 2025). "The most important markers of TAMs have been identified by studying tumours at different sites: CD163, CD204 (MSR1), CD206 (MRC1), MARCO, SIGLEC1 (CD169), stabilising protein-1 (Stab1) and Tie2 (TEK)." (PMID 39060648, 2024). "The directly interaction between SIGLEC1+ macrophage and SPN+ T cell possibly expedited tumor cell lymph node metastasis." (PMID 36709495, 2023). "During tumor progression, CAPZA1, GRB2, NF2EL3, PLEKHO1, SIGLEC1, and UBE2Z were expressed at higher levels in late-stage KIRC, whereas EMX2, FUCA1, IMPA2, and RORC were expressed at higher levels in early-stage KIRC." (PMID 35127943, 2022). "CAPZA1, HLA-E, IMPA2, NFE2L3, PLEKHO1, SIGLEC1, and UBE2Z were expressed at higher levels in tumor tissues, whereas EMX2, FGL2, FUCA1, and GRB2 were expressed at lower levels in tumor tissues." (PMID 35127943, 2022). "Among them, VSIG4, SIGLEC1, and CXCL13 were significantly positively correlated with estimate scores, stromal scores, and immune scores in pan-cancer, while negatively correlated with tumor purity." (PMID 36544770, 2022). "Some M1 markers (IL1A, IL1B, CD86), M2 markers (CCL18, MRC1/CD206, CSF1R), and TAM markers (HLA-DR, IL1RN, CD163, ITGAM, SIGLEC1/CD169) were highly expressed on both tumor and non-tumor macrophages." (PMID 33918618, 2021).
tumor (continued). "In addition, using the TIMER algorithm, we found that expression of TMEM150B, SIGLEC1, and CTSW correlated positively with the tumor infiltration levels of B cells, CD8+ T cells, CD4+ T cells, macrophages, and dendritic cells." (PMID 32074080, 2020). "Importantly, SIGLEC‐1 expression has been leveraged for immunotherapy: ganglioside‐containing liposomes targeting SIGLEC‐1 on tDCs have been used in a nanovaccine platform incorporating the TLR7/8 agonist R848 and tumor antigen payloads." (PMID 41275417, 2025). "Since former studies have found SIGLEC1 (CD169), SIGLEC2 (CD22), SIGLEC3 (CD33), SIGLEC7, SIGLEC9, and SIGLEC15 expressed by immune cell populations could be manipulated by tumor cells to escape immune surveillance, we focused on the five SIGLEC family members." (PMID 33240817, 2020). "SIGLEC1, also named as CD169, could function as a facilitator of the recognition and internalization of sialic acid decorated apoptotic bodies and exosomes derived from tumors, which potentially contributes to both attenuation and facilitation of anti-tumor immunity." (PMID 32717065, 2020).